CLOCK (clock circadian regulator)
Diseases named in the same sentence as CLOCK in open-access papers (continued):
Sharing a sentence is not in itself a finding about the gene and the disease.
ovarian carcinoma (6 papers, 2019 to 2025). A malignant neoplasm originating from the surface ovarian epithelium. "The expression of CLOCK mRNA and protein is greatly increased in cisplatin-resistant ovarian cancer cells, whereas CLOCK knockdown significantly increases anti-proliferative and pro-apoptotic effects of cisplatin in resistant cells." (PMID 33114496, 2020). "A study verifying the link between the CLOCK gene and cisplatin resistance treated cisplatin-resistant and cisplatin-sensitive ovarian cancer cells with varying concentrations of cisplatin." (PMID 33364523, 2020). "Increased expression of CLOCK endowed resistance of ovarian cancer cells to cisplatin treatment." (PMID 40495887, 2025). "Altogether, these studies indicate that the CLOCK gene may be a novel candidate for targeted therapy in drug-resistant ovarian cancer." (PMID 33114496, 2020). "We further evaluated the correlations between PER1 and these 10 interacting proteins based on the GEPIA database and found that the expression of PER1 in ovarian cancer was correlated with that of ARNTL, CLOCK, CRY1, CRY2, CSNK1D, CSNK1E, NPAS2, and PER3." (PMID 34220965, 2021).
cataract (5 papers, 2010 to 2022). Partial or complete opacity of the crystalline lens of one or both eyes that decreases visual acuity and eventually results in blindness. "Does the increased age-dependent incidence of cataracts in CLOCK-deficient mice reflect whole-body ROS status, or local events such as oxygen tension and ion transport in the lens epithelia?" (PMID 21566258, 2011). "They report that CLOCK-deficient mice have reduced average and maximum lifespan, and have increased incidence of dermatitis and cataracts as the animals age." (PMID 21566258, 2011). "CLOCK deficiency also results in the development of two age-specific pathologies in these mice, cataracts and dermatitis, at a much higher rate than in wild type mice." (PMID 21149897, 2010). "Development of cataracts upon CLOCK deficiency is more specific." (PMID 21149897, 2010). "Similarly, what does the higher incidence of cataracts in CLOCK-deficient mice mean?" (PMID 21566258, 2011). "Thus, deficiency of CLOCK results in the early development of cataracts in mice." (PMID 21149897, 2010). "By ~28 months, more than 70% of male and 90% of female CLOCK KO mice had cataracts, with cataracts evident as early as 11 months of age for females and 14 months for males." (PMID 36009235, 2022). "For instance, similar to Bmal1−/− mice, Clock−/− mice have a reduced lifespan and develop age-specific pathologies such as cataracts and dermatitis, suggesting an important role of CLOCK in aging." (PMID 36618934, 2022). "CLOCK KO mice did not have such a reduced lifespan compared to BMAL1 KO mice but did develop cataracts, although the type of cataract was not specified." (PMID 36009235, 2022).
dermatitis (5 papers, 2010 to 2022). An inflammatory process affecting the skin. "Histological examination and assessment of constituent cell populations is necessary to relate the observation of increased dermatitis incidence in CLOCK-deficient mice to epithelial, mast, and dendritic cells, sebaceous glands and hair follicles." (PMID 21566258, 2011). "CLOCK and BMAL1 proteins were recently implicated in the regulation of the hair cycle and hair follicle stem cell proliferation, thus, CLOCK deficiency can affect skin epithelium homeostasis, which also can contribute to the development of dermatitis." (PMID 21149897, 2010). "At this time we cannot identify the cause of dermatitis in Clock−/− mice, but our data suggests that CLOCK and probably other circadian proteins play an important role in the aging of skin and support further studies on this subject." (PMID 21149897, 2010). "What does a higher incidence and earlier onset of dermatitis in CLOCK-deficient mice mean?" (PMID 21566258, 2011). "For example, experimental studies in mice have shown that genetic disruption of the circadian protein CLOCK promotes dermatitis." (PMID 34204077, 2021). "CLOCK and BMAL1 are involved in the control of memory and adaptation to novelty therefore, at this time we cannot exclude the possibility that increased dermatitis in Clock−/− mice is a consequence of changes in behavioral patterns; the detailed study of Clock−/− behavior is currently in progress." (PMID 21149897, 2010).
inflammatory bowel disease (5 papers, 2022 to 2025). A spectrum of small and large bowel inflammatory diseases of unknown etiology. "Other studies showed that inflammatory bowel disease (IBD) patients exhibit suppressed CLOCK and BMAL1 expression in intestinal epithelial cells coupled to dysbiosis and aberrant immune activation." (PMID 41262263, 2025).
pancreatic cancer (5 papers, 2020 to 2024). "Reduced CLOCK expression within pancreatic tumors is associated with decreased survival time." (PMID 33302582, 2020). "Previous studies have identified many polymorphisms affecting multiple clock genes (BMAL1, CLOCK and NPAS2) that are linked to increased risks in prostate, breast, ovarian and pancreatic cancers." (PMID 36978001, 2023). "In contrast, CLOCK expression is significantly reduced in ovarian and pancreatic cancer." (PMID 33302582, 2020).
Parkinson disease (5 papers, 2018 to 2025). A progressive degenerative disorder of the central nervous system characterized by loss of dopamine producing neurons in the substantia nigra and the presence of Lewy bodies in the substantia nigra and locus coeruleus. "In a Chinese population, CLOCK rs1801260 polymorphism was associated with an increased risk of Parkinson’s disease." (PMID 34068889, 2021).
Abdominal obesity (4 papers, 2022 to 2024). Excessive fat around the stomach and abdomen. "The polymorphism rs1801260 (T > C) in the CLOCK gene has been linked to several behavioral and physiological changes, including reduced sleep duration, increased energy intake, frequent snacking, skipping breakfast, higher BMI, and greater abdominal obesity." (PMID 39203789, 2024). "In females, both genotypes of CLOCK rs9312661 in the VLFC showed an increased incidence of abdominal obesity compared with the reference group (AA genotype, OR: 2.26, 95% CI: 1.43–3.56, p = 0.0005; GA/GG genotype, OR: 2.11, 95% CI: 1.38–3.23, p = 0.0005)." (PMID 35276838, 2022). "In the female VLFC, the major homozygous allele of CLOCK rs11932595 and CRY1 rs3741892 had a higher abdominal obesity risk than those in the OFC." (PMID 35276838, 2022).
atherosclerosis (4 papers, 2021 to 2025). A disease characterized by the build-up of fatty material and calcium deposition in the arterial wall resulting in partial or complete occlusion of the arterial lumen. "Our prior study has shown that IF improves acrolein-induced atherosclerosis by regulating the expression of CLOCK/BMAL1." (PMID 40423448, 2025). "Our previous studies have shown that acrolein, an environmental pollutant, promotes atherosclerosis by downregulating the circadian clock genes (CLOCK/BMAL1) and disrupting circadian rhythm." (PMID 40423448, 2025). "Our antecedent study has also established that intermittent fasting (IF) improves acrolein-induced atherosclerosis by regulating the expression of CLOCK/BMAL1." (PMID 40423448, 2025). "Our previous study has indicated that IF improves acrolein-induced atherosclerosis by regulating the expression of CLOCK/BMAL1." (PMID 40423448, 2025). "The circadian gene CLOCK has protective effects against atherosclerosis." (PMID 33557283, 2021). "However, whether melatonin alleviates atherosclerosis through CLOCK and BMAL1 regulation is unknown." (PMID 33557283, 2021). "In short summary, disruption of the circadian clock at different nodes (BMAL1, CLOCK, CRYs, PERs, and REV-ERB) promotes atherosclerosis." (PMID 33445491, 2021). "Our previous studies showed that acrolein, an environmental pollutant, exacerbated atherosclerosis by reducing CLOCK/BMAL1 levels and disrupting circadian rhythm; in contrast, intermittent fasting (IF), a dietary regimen, ameliorated acrolein-induced atherosclerosis." (PMID 38807423, 2024).
Cluster headache (4 papers, 2018 to 2025). A type of headache characterized by repeated attacks of unilateral pain lasting 15 to 180 minutes and associated with local autonomic signs. "One study reported a significant association between rs12649507 SNP in the CLOCK gene and cluster headache susceptibility and this association strengthened when stratified for reported diurnal rhythmicity of attacks." (PMID 39560176, 2025). "Several studies have investigated the role of the rs1801260 polymorphism of the circadian locomotor output cycles kaput (CLOCK) gene in cluster headache but did not report an association." (PMID 39560176, 2025). "The WGS on four members of the large multigenerational French family of cluster headache found that two family members showing the same phenotypic circadian pattern (familial periodicity) of symptoms had two genetic risk loci in the HCRTR2 and in the CLOCK genes." (PMID 39560176, 2025).
cognitive deficits (4 papers, 2017 to 2024). "We further demonstrated in a previous study that CLOCK regulates human cortical neuronal migration as well as gene networks implicated in cognitive disorders, such as ASD and ID." (PMID 35431788, 2022). "More recently, Bessi and colleagues reported that CLOCK T3111C polymorphism interacts with cardiovascular risk factors in individuals with subjective and mild cognitive impairment, influencing the risk of conversion to AD." (PMID 34921659, 2022). "As a result, four SNPs, including the RORA-rs13329238, NPAS2-rs17655330, CLOCK-rs3749473, and RORB-rs10781247 SNPs individually and interactively alters the hazard of cognitive deficits in terms of MMSE scores for normal aging." (PMID 29209239, 2017). "Weighted gene co-expression network analysis (WGCNA) have identified CLOCK as a hub gene involved in cognitive disorder genes rather than in known circadian genes." (PMID 35431788, 2022).
colon carcinoma (4 papers, 2018 to 2024). "For Ireb2, the mRNA phase — maximal abundance around ZT10 — was in principle compatible with the BMAL1:CLOCK regulation reported from colon cancer cells." (PMID 38773499, 2024). "Krugluger et al41 found that CLOCK is more abundantly expressed in colon cancer tissues than in normal tissue." (PMID 30013305, 2018). "Furthermore, the same study demonstrated an increased resistance to paclitaxel in human colon cancer cells overexpressing CLOCK and BMAL1." (PMID 39463009, 2024). "CLOCK and BMAL1 overexpression also inhibits cell growth and stalls G1 to S phase transition in human colon cancer cells." (PMID 39463009, 2024). "Moreover, it has been reported that in colon cancer cells, the Ireb2 gene is circadianly transcribed through BMAL1:CLOCK, engendering Ireb2 mRNA and IREB2/IRP2 protein oscillations that subsequently regulate Tfrc stability in a rhythmic fashion." (PMID 38773499, 2024). "Additionally, CLOCK gene upregulation predicts poorer outcome in CRC patients, upholds colon cancer cell proliferation, and reduces apoptosis." (PMID 31311174, 2019).
hyperlipidemia (4 papers, 2012 to 2022). "However, morning exercise is superior to night exercise in enhancing insulin sensitivity and glucose transport, but night exercise is likely to improve mitochondrial networks and morphology through CLOCK–mitophagy and further alleviate apoptosis, thereby reducing fat infiltration and hyperlipidemia." (PMID 36012573, 2022).
neuroblastoma (4 papers, 2007 to 2022). Neuroblastoma (NB) is the most common solid, extracranial childhood tumor. "Although ldha has a canonical E-box and has been shown to be activated by both NPAS2 and CLOCK in a neuroblastoma cell line, mRNA levels of this gene were surprisingly stable across time-of-day, experimental condition, and genetic background." (PMID 17945005, 2007). "Furthermore, TBX2 acts as a neuroblastoma core regulatory circuitry component that promotes MYCN/FOXM1-mediated reactivation of DREAM targets, while CLOCK genes are closely associated with cancer development, particularly in endocrine tissues." (PMID 32391054, 2020). "Similarly, HIF-1α cooperates with BMAL1/MOP3 and CLOCK to regulate gene expression in a cell line of mouse neuroblastoma." (PMID 32823749, 2020).
psoriasis (4 papers, 2022 to 2025). An autoimmune condition characterized by red, well-delineated plaques with silvery scales that are usually on the extensor surfaces and scalp. "Moreover, the CLOCK gene is associated with the regulation of psoriasis by modulating the expression of interleukin-23R in mice." (PMID 37237866, 2023). "In another mouse model where psoriasis was induced via TLR7, CLOCK and Per2 were found to regulate the severity of psoriasis via the direct modulation of the expression of IL23R." (PMID 36982706, 2023).
Sepsis (4 papers, 2021 to 2025). Sepsis is defined as life-threatening organ dysfunction caused by a dysregulated host response to infection. "Genes promoting sepsis progression including CLOCK, PPBP and Rho family GTPASE 2 (RND2) were upregulated in Native Hawaiian patients." (PMID 36450776, 2022). "Circadian rhythm disruption and dysregulation of CLOCK genes such as Bmal1, are reported in sepsis patients." (PMID 36865524, 2022). "Mice with the circadian gene CLOCK deleted demonstrate increased survival outcomes compared with wild type mice in a polymicrobial sepsis preclinical model." (PMID 36450776, 2022). "The upregulation of the CLOCK gene in the Native Hawaiian CRC-sepsis cohort suggests that this may be a potential negative prognosis marker." (PMID 36450776, 2022).
viral infection (4 papers, 2012 to 2026). "The CLOCK/BMAL1 complex regulates the expression of pattern recognition receptors (PRRs) involved in nucleic acid sensing during viral infections, an essential function of the innate immune system." (PMID 40284797, 2025). "Functionally, CLOCKΔ19 produces β-catenin stabilization in T cells, pronounced expansion of RORγt+ CD4+ T cells and Treg cells, impaired Treg suppression of Th17 responses, heightened Th17 responses, and reduced IFN-γ production during viral infection." (PMID 41928813, 2026). "Interestingly, a recent report indicates that CLOCK and BMAL1 play a role in transcriptional activation after viral infection." (PMID 22900038, 2012). "CLOCK, BMAL1, and REV-ERB regulate the expression of the pattern recognition receptors (PRRs) that recognize viral nucleic acids during viral infections, and cells lacking Bmal-1 are more vulnerable to infection by RNA virus infection." (PMID 37999239, 2023).
allergic disease (3 papers, 2018 to 2025). An immune response that occurs following re-exposure to an innocuous antigen, and that requires the presence of existing antibodies against that antigen. "CLOCK temporally gates the mast cell and basophil response to IL-33 via regulation of ST2 expression, which may also underlie circadian nature of allergic disease." (PMID 32595651, 2020). "Altered protein levels of CLOCK, BMAL1, REV-ERBs, and RORs in eosinophils from asthmatics reflected the disease severity and allergy status of the patients." (PMID 40131242, 2025).
attention deficit-hyperactivity disorder (3 papers, 2010 to 2021). A disorder characterized by a marked pattern of inattention and/or hyperactivity-impulsivity that is inconsistent with developmental level and clearly interferes with functioning in at least two settings (e.g. at home and at school). "One noncoding polymorphism in the 3′-UTR of the human CLOCK gene (a T-to-C transition, rs1801260) is associated with adult attention-deficit and hyperactivity disorder (ADHD)." (PMID 26019524, 2014).
gastric cancer (3 papers, 2018 to 2024). A primary or metastatic malignant neoplasm involving the stomach. "NR1D1 and NR1D2 are transcription factors that bind ROREs and act as transcriptional repressors to inhibit the expression of BMAL1:CLOCK, underlining the importance of considering circadian rhythms in gastric cancer development and treatment." (PMID 39062777, 2024). "In gastric cancer our group suggested that rs1801260 C allele affect patient survival only if combined with the major allele of CLOCK rs3749474." (PMID 30518396, 2018). "The up-regulation of BMAL1, CLOCK, and PER in gastric cancer and the up-regulation of CRY1 in more advanced stage gastric cancer but not in the earlier stage has also been reported." (PMID 34966277, 2021).
Glucose intolerance (3 papers, 2022 to 2025). Glucose intolerance (GI) can be defined as dysglycemia that comprises both prediabetes and diabetes. "In addition, K6 probiotics significantly mitigated SD-induced weight loss, exercise performance decrement, glucose intolerance, inflammation (TNF-α, IL-1β), tight junction hyperpermeability (Claudin-1, ZO-1), and circadian dysregulation (BMAL-1, CLOCK)." (PMID 40959574, 2025).
Infertility (3 papers, 2013 to 2022). "Targeted ablation of these circadian proteins BMAL1 and CLOCK results in infertility in mice with significant characteristic morphological alterations of CBs which are clearly different from those observed in mice lacking pGRTH (KI) and GRTH null mice." (PMID 33425888, 2020). "Genotype and allelic distribution of the CLOCK and ARNTL polymorphisms of the 517 infertile men and 444 fertile controls." (PMID 23527142, 2013). "Another possible mechanism could be the genetic dysregulation of biological clock, since the CLOCK gene was shown to play an important role between circadian disruption and infertility." (PMID 35620388, 2022).
multiple sclerosis (3 papers, 2018 to 2022). A progressive autoimmune disorder affecting the central nervous system resulting in demyelination. "Our aim was to analyse selected polymorphisms of ARNTL and CLOCK, and their association with multiple sclerosis." (PMID 29324865, 2018). "The ARNTL rs3789327 CC genotype was associated with higher risk for multiple sclerosis at an OR of 1.67 (95% CI 1.35–2.07, P = 0.0001) and the CLOCK rs6811520 genotype CC at an OR of 1.40 (95% CI 1.13–1.73, P = 0.002)." (PMID 29324865, 2018). "The results of this study suggest that genetic variability in the ARNTL and CLOCK genes might be associated with risk for multiple sclerosis." (PMID 29324865, 2018). "We hypothesized that this fact might be partially associated with the influence of latitude on circadian rhythm and consequently that genetic variability of key circadian rhythm regulators, ARNTL and CLOCK genes, might contribute to the risk for multiple sclerosis." (PMID 29324865, 2018). "Of note, enhanced risk of multiple sclerosis has been associated with variations in the circadian genes ARNTL/BMAL1 and CLOCK, likely due to the regulatory role of the ARNTL gene in oligodendrogenesis." (PMID 36299487, 2022). "Indeed, circadian dysregulation has been associated with myelination disorders in the central nervous system, i.e. enhanced risk of multiple sclerosis correlated with mutations in ARNTL/BMAL1 and CLOCK circadian genes, owing to the regulatory role of the ARNTL gene in oligodendrogenesis." (PMID 36299487, 2022).
osteosarcoma (3 papers, 2013 to 2023). A usually aggressive malignant bone-forming mesenchymal neoplasm, predominantly affecting adolescents and young adults. "We also identified functional E-boxes in the ANGPTL2 promoter and observed occupancy of these sites by endogenous CLOCK in human osteosarcoma cells." (PMID 23469106, 2013). "We selected the immortalized human osteosarcoma cell line U2OS to identify and characterize binding sites of the circadian transcription factor CLOCK/BMAL1 and its inhibitor CRY1 by chromatin immunoprecipitation and next generation sequencing (ChIP-seq)." (PMID 25007071, 2014). "To further investigate the function of E-boxes in CLOCK/BAML1-mediated ANGPTL2 expression, we initially performed real-time PCR analysis using total RNA extracted from the human osteosarcoma cell line U2OS, a well characterized line used to investigate circadian rhythms." (PMID 23469106, 2013).